FIZ1 (FLT3 interacting zinc finger 1)
Description:
May be a transcriptional repressor of NRL function in photoreceptors. Does not repress CRX-mediated transactivation (By similarity).
Synonyms: ZNF798; FLJ14768
Tractability: PROTAC: ubiquitination databases record sites on it.
Gene: Protein-coding gene on chromosome 19 (55,591,371 to 55,606,194, reverse strand). Ensembl gene ENSG00000179943.
Subcellular location: Cytoplasm; Nucleus
Subcellular location (Human Protein Atlas): Nucleoplasm
Gene Ontology:
Molecular function: receptor tyrosine kinase binding; RNA polymerase II-specific DNA-binding transcription factor binding; transcription coactivator activity
Biological process: positive regulation of transcription by RNA polymerase II
Cellular component: chromatin; cytoplasm; nucleus
Genetic constraint (gnomAD): Loss-of-function variants: 2 observed, 5.28 expected, observed/expected ratio (o/e) 0.38, 90% interval 0.15 to 1.18. That is too few expected variants to judge how well the gene tolerates losing a copy. Missense variants: 606 observed, 584.3 expected, observed/expected ratio (o/e) 1.04, 90% interval 0.97 to 1.11. Synonymous variants: 388 observed, 294.59 expected, observed/expected ratio (o/e) 1.32, 90% interval 1.21 to 1.43.
Homologues: Orthologues: chimpanzee FIZ1 (99% identical), macaque FIZ1 (97% identical), pig FIZ1 (93% identical), dog FIZ1 (92% identical), mouse Fiz1 (87% identical), rat Fiz1 (87% identical), guinea pig FIZ1 (83% identical), Drosophila melanogaster CG31224 (34% identical). Paralogues in human: ZNF618 (19% identical), ZBTB44 (13% identical).
Diseases named in the same sentence as FIZ1 in open-access papers:
FIZ1 is named in the same sentence as 4 diseases in open-access papers, as found by Europe PMC text mining. Sharing a sentence is not in itself a finding about the gene and the disease. The quoted sentences say what the papers report.
breast carcinoma (1 paper, 2018). "However, FIZ1 expression in breast cancer is statistically associated with progesterone receptor status, estrogen receptor status, and sample subtype, and it undergoes extensive CpG-island methylation, and it is therefore an intriguing candidate for further study." (PMID 30483308, 2018).
FIZ1 also shares sentences with these, for which no sentence is quoted: acute kidney injury (1 paper); hyperprolinemia type 2 (1); mastitis (1).